TCF4 (transcription factor 4)
Diseases named in the same sentence as TCF4 in open-access papers (continued):
Sharing a sentence is not in itself a finding about the gene and the disease.
gastric cancer (36 papers, 2008 to 2025). A primary or metastatic malignant neoplasm involving the stomach. "SETDB1 is induced by H. pylori infection through TCF4, suggesting a mechanism for this infection, which is associated with gastric cancer, to promote cell proliferation." (PMID 41425714, 2025). "In gastric cancer, The β-catenin/TCF4 transcriptional complex induces GPX4 expression, thereby inhibiting ferroptosis." (PMID 41213915, 2025). "Circ_SMAD4 promotes gastric cancer tumorigenesis by recruiting TCF4 to facilitate CTNNB1 transcription in the nucleus and sequestering miR-1276 in the cytoplasm to prevent the silencing of CTNNB1 mRNA, thereby activating the Wnt/β-catenin pathway." (PMID 40708910, 2025). "Polymerase theta (POLQ), a DNA polymerase, drives resistance to ferroptosis in gastric cancer cells by stimulating DHODH expression via the transcription factor E2F transcription factor 4 (E2F4)." (PMID 39624080, 2024). "β-Catenin responsive transcription inhibitor 3/5 (iCRT3/5), which mainly blocks β-catenin-TCF4 interactions, is in the preclinical stage of gastric cancer treatment, and it can kill gastric cancer malignant cells and inhibit gastric cancer development." (PMID 38952556, 2024). "For example, ESRRG has been shown to antagonize the proliferation of gastric cancer cells by suppressing TCF4/LEF1 binding to the CCND1 promoter, highlighting its tumor suppressor role." (PMID 37679788, 2023). "ESRRG has been identified as a candidate tumor suppressor gene in gastric cancer that can inhibit Wnt signaling via the suppression of transcription factor 4 (TCF4)/lymphoid enhancer-binding factor 1 (LEF1), binding to the Cyclin D1 (CCND1) promoter." (PMID 37240447, 2023). "G17 was also observed to induce the migration and invasion of gastric cancer SGC-7901 cells through the β-catenin/TCF-4 pathway." (PMID 34976177, 2022). "Follistatin-like 1 (FSTL1), miR-23b, ETS1, and TCF4 have all been reported to be prognostic biomarkers for gastric cancer patients, mainly involved in tumor progression and tumor immunity." (PMID 34980151, 2022). "We found in this research that β-catenin/TCF-4 complex was aberrantly activated in precursors of gastric cancer, and that GRb1 treatment disrupted the interaction of β-catenin with TCF-4." (PMID 34594214, 2021). "In gastric cancer cells, Wtn3a stimulation promotes SMYD3 transcript expression, through the direct recruitment of β-catenin/TCF4 complex in Wnt3a-treated SGC7901 gastric cancer cells." (PMID 31935919, 2020). "We further investigated the functional significance of wnt/β-catenin signaling activation in miR-501-5p–mediated self-renewal of gastric cancer cells by silencing β-catenin or expressing TCF4-dn in miR-501-5p–overexpressing MGC-803 and SGC-7901 cells." (PMID 27846906, 2016). "Similarly, Helicobacter pylori (H. pylori) infection induces SETDB1 expression in a TCF4-dependent manner, which contributes to gastric cancer formation." (PMID 38057834, 2023). "Furthermore, high expression of ETS1 and TCF4 indicated poor prognosis, suggesting that ETS1 and TCF4 are potential prognostic biomarkers for gastric cancer." (PMID 34686186, 2021). "In addition, overexpression of EPHA2 can regulate the proliferation, migration, invasion, and morphology of gastric cancer cells by upregulating TCF4, CyclinD1, and c-Myc in the Wnt/β-catenin signaling pathway." (PMID 33834064, 2021). "In addition, it is proved that gastrin functions as a stimulator of the metastasis of gastric carcinoma through the β-catenin-TCF4 pathway." (PMID 33937399, 2021). "Furthermore, increased nuclear β-catenin levels, induces TCF4 transcription factor activation, β-catenin/TCF4 complexing and the induction of cMyc, Cyclin D and c-Jun β-catenin/TCF4 target gene expression in gastric cancer cells, promoting proliferation." (PMID 32536347, 2020).
gastric cancer (continued). "Moreover, sphere formation assays indicated that silencing β-catenin or expressing TCF4-dn abrogated the promotive effects of miR-501-5p on self-renewal of gastric cancer cells." (PMID 27846906, 2016). "The expression level of TCF4 decreased in most tumors except acute myeloid leukemia (AML), esophageal cancer, pancreatic cancer, renal cell carcinoma, and stomach cancer." (PMID 39205642, 2024). "The β-catenin/TCF4 complex, by promoting the expression of GPX4, confers resistance to ferroptosis in gastric cancer cells." (PMID 39532842, 2024). "LF3 is a 4-thioureido-benzenesulfonamide derivative that profoundly inhibits the interaction between β-catenin and TCF4 and reduces the expression of GPX4, inducing iron-induced death in gastric cancer cells." (PMID 38952556, 2024). "The β-catenin/TCF4 transcriptional complex directly binds to the GPX4 promoter region and induces its expression, thereby inhibiting ferroptosis in gastric cancer cells." (PMID 39309441, 2024). "MiRNAs can not only be used as biomarkers of gastric cancer, but also affect Akt and Akt, NF-κB, RAGE, ARF6, TCF4, STAT3 and other signaling pathways promote or inhibit the occurrence and development of gastric cancer." (PMID 35093110, 2022). "In addition, we checked signalling molecules downstream of β-catenin and found that TCF-4, c-Myc and Cyclin D1 were reduced in Mist1-overexpressing cells, which indicates that the Wnt/β-catenin signalling pathway was inhibited in Mist1-overexpressing gastric cancer cells." (PMID 34149921, 2021). "In gastric cancer cells, TGF-β-driven RUNX3 antagonized WNT-signaling via a RUNX3/TCF4/β-catenin complex, which in our model would result in suppression of hypertrophy." (PMID 32195247, 2020). "Of various transcription factors that suppress expression of E-cadherin including Snail, Slug, Twist, TCF4 and SIP1, expression of Snail was specifically modulated by NDRG1 in gastric cancer cells." (PMID 22844455, 2012). "In fact, ETS1 and TCF4 expression are significantly upregulated in advanced gastric cancer tissues, suggesting that ETS1 and TCF4 may be involved in tumor growth and progression." (PMID 34686186, 2021). "In gastric cancer, CCND1 has been shown to directly interact with TCF4 through the Wnt signaling pathway, suggesting that other mechanisms of CCND1 overexpression may also occur in MM." (PMID 31156714, 2019). "It will be of interest to determine whether the expression of PLA2G3 is related to the activation of the Wnt/β-cat/Tcf-4 pathway, as already suggested for PLA2G2A in gastric cancer." (PMID 18212756, 2008).
lung carcinoma (32 papers, 2007 to 2025). "Emodin-containing Pc-Ex exerted therapeutic effects on lung cancer-associated cachexia by inhibiting TCF4/TWIST1 complex-induced PTHrP expression." (PMID 35406121, 2022). "This study demonstrated the molecular mechanisms underlying the TCF4/TWIST1 interaction-mediated PTHrP expression in lung cancer-induced cachexia." (PMID 35406121, 2022). "In lung cancer, TCF-4 positively regulates lncRNA XIST expression in TAM by directly binding to the promoter region of XIST gene." (PMID 36263199, 2022). "The research suggested that lncRNA XIST can regulate the expression of TCF-4, and then regulate the polarization of macrophages in lung cancer." (PMID 35109760, 2022). "The PTHLH mRNA levels were upregulated upon TCF4 overexpression and downregulated upon TCF4 silencing in lung cancer cells." (PMID 35406121, 2022). "The results showed that lncRNA XIST positively regulated the M2 polarization and interacted with TCF-4, thus regulating the development of lung cancer." (PMID 35145526, 2022). "In this study, Pc-Ex, which contains emodin as a major component, sufficiently suppressed the PTHLH mRNA and PTHrP expression levels in lung cancer cells stimulated with TGFβ1 by inhibiting the interaction between TCF4 and TWIST1." (PMID 35406121, 2022). "We found that PGC1α functions as a tumor suppressor of the TCF4-TWIST1-induced EMT transcriptional circuit in lung cancer malignancy via increasing ID1 expression, which can competitively bind to TCF4." (PMID 33917757, 2021). "The downregulated TCF-4 was reported to comprehensively inhibit the proliferative and invasive ability of lung cancer cells." (PMID 32657761, 2020). "Along with the examination of TC1, expression levels of DNMT1, β-catenin, TCF4, Axin, Dab2, and Chibby were also examined in 84 lung cancer specimens." (PMID 28968956, 2017). "We thus examined the correlation between TC1 and other Wnt pathway members including β-catenin, Chibby, TCF4, Axin, and Dab2 in lung cancers." (PMID 28968956, 2017). "Actually, we demonstrated that the TCF-4/MMP-15 pathway was causally linked to the invasion and metastasis of lung cancer cells." (PMID 27046058, 2016). "Transfection of axin gene decreases TCF-4 expression and inhibits the proliferation and invasive ability of lung cancer cells." (PMID 27046058, 2016). "Here in this study, we identified MMP-15 as a target gene of TCF-4 in lung cancer cells, providing a mechanism linking Wnt signaling and TCF-4 to the metastasis and progression of lung cancer." (PMID 27046058, 2016). "Both TCF-4 and MMP-15 are closely linked to the development of lung cancer, while the regulatory role of TCF-4 in MMP-15 expression is still obscure." (PMID 27046058, 2016). "In the present study, we identified that at least MMP-15 was rather important in TCF-4-midiated metastasis of lung cancer." (PMID 27046058, 2016). "To observe the association between TCF-4 and MMP-15 in lung cancer, we firstly demonstrated that both TCF-4 and MMP-15 mRNA levels were notably elevated in lung cancer cells (H460, A549 and LLC) versus the normal epithelial cells SAEC." (PMID 27046058, 2016). "It has been recently suggested that TCF4 plays an important role in the carcinogenesis of lung cancer as demonstrated by its high expression in cancer samples." (PMID 17667922, 2007). "Emodin inhibits transcription Factor 4 (TCF4)- Twist family bHLH transcription factor 1 (TWIST1) complex formation, thereby suppressing parathyroid hormone-like hormone (PTHLH) protein expression, which are implicated in lung cancer cachexia." (PMID 40490812, 2025). "The PTHLH mRNA levels were upregulated in lung cancer cells ectopically overexpressing Myc-TCF4." (PMID 35406121, 2022). "However, lncRNA XIST knockout can restore IL-4-induced M2 polarization, further indicating the importance of TCF-4 in M2 Mφs and TAMs-induced proliferation, migration and invasion of lung cancer cells." (PMID 35145526, 2022).
lung carcinoma (continued). "In addition, overexpression of Pygo1 in lung cancer cells led to an increase of β-catenin/TCF4 complex, as well as upregulated expression of target genes of β-catenin." (PMID 36398031, 2022). "Conversely, TCF4 knockdown downregulated PTHLH expression in lung cancer cells." (PMID 35406121, 2022). "Similarly, Tcf4 has been shown to play a role in developing lung cancer, for example, by promoting M2 polarization of macrophages." (PMID 35391793, 2022). "TGFβ1-induced PTHLH expression was mitigated in TCF4-silenced A549 and Calu-1 lung cancer cells." (PMID 35406121, 2022). "In addition, upregulated TCF4 levels have been observed in a highly bone-metastatic subpopulation of H460 lung cancer cells." (PMID 33917757, 2021). "Blockage of the TCF-4/MMP-15 pathway might represent an effective strategy to manage the therapy of lung cancer in clinic." (PMID 27046058, 2016). "High expression of TCF-4 is positively correlated with lung cancer progression." (PMID 27046058, 2016). "Furthermore, we demonstrated that NIFK modulates lung cancer metastasis by regulating TCF4/β-catenin signaling via the alternation of Casein kinase 1α (CK1α) expression." (PMID 26984280, 2016). "We hypothesized that administration of BC-23 might improve the action of radiotherapy on lung cancer cells through the inhibition of β-catenin/Tcf4 interaction and signaling." (PMID 27014877, 2016). "Moreover, in vitro experimental data showed that overexpression of Pygo1 in lung cancer cells could promote β-catenin/TCF4 complex formation." (PMID 36398031, 2022). "Furthermore, since the Wnt signaling pathway plays a critical role in progression of tumor cells, TCF-4 expression could influence cancer cells in their cellular activities and development of lung cancer." (PMID 30867651, 2019). "Therefore, we concluded that TCF-4 expression might positively correlate with MMP-15 levels in lung cancer." (PMID 27046058, 2016). "However, whether those targets were still regulated by TCF-4 and which one was the most important in lung cancer were still obscure." (PMID 27046058, 2016). "In this study, the interaction between TCF4 and TWIST1 upregulated PTHLH expression and consequently promoted lung cancer growth and cachexia." (PMID 35406121, 2022). "The interaction between TCF4 and TWIST1 promotes lung cancer growth, metastasis, and cachexia by upregulating the expression of PTHLH and EMT-related genes." (PMID 35406121, 2022). "Consistent with this, suppression of ID1 increased promoter occupancy of TCF4 and TWIST1 on E-box containing CDH1 and CDH2 promoter loci, and increased TCF4 and TWIST1 were observed on CDH1 and CDH2 promoters in FOXA1 knockdown A549 lung cancer cells." (PMID 35897813, 2022). "Previous studies have demonstrated that TCF4 can interact with TWIST1 to promote the expression of EMT-related genes, such as CDH2, VIM, SNAI1, and SNAI2, in embryonic stem and lung cancer cells." (PMID 35406121, 2022). "The upregulation of TCF-4/lncRNA XIST contributes to TAM phenotypic transformation and M2 polarization, which drive tumor progression in lung cancer." (PMID 36263199, 2022). "The interaction between TCF4 and TWIST1 upregulated PTHLH expression in lung cancer cells in response to TGFβ1 stimulation." (PMID 35406121, 2022). "Here, we suggest that cooperation of TCF4-TWIST1 controlled by the PGC1α-ID1 transcriptional axis mediates EMT and lung cancer metastasis, and that this molecular framework is an attractive target for lung cancer diagnosis and treatment." (PMID 33917757, 2021). "NIFK activates TCF4/β-catenin signaling and Ki-67-dependent cell proliferation regulation through RUNX1-dependent CK1α repression and participates in the progression of lung cancer." (PMID 34712323, 2021).
lung carcinoma (continued). "Knockdown of TCF-4 also suppressed the expression of OPN, which indicates that β-catenin, as well as TCF4, is essential for the OPN expression in lung cancer cells." (PMID 29254164, 2017). "Here we found that expression of TCF-4 and MMP-15 was increased in lung cancer cells or tissues versus the normal ones." (PMID 27046058, 2016). "In conclusion, we are the first to identify TCF-4 as a co-activator of NF-κB p65 to promote MMP-15 transcription and potentiate the migration activity of lung cancer cells." (PMID 27046058, 2016). "In conclusion, we are the first to identify TCF-4 as a co-activator of NF-κB p65 to promote MMP-15 transcription and potentiate the migration activity of the lung cancer cells." (PMID 27046058, 2016). "We demonstrate that Axin downregulates TCF-4 transcription and TCF-mediated gene transcription in a β-catenin-dependent manner in lung cancer cells." (PMID 20122174, 2010). "However, it is not fully understood which stimuli and signaling cascades fine-tune TCF4- and TWIST1-mediated EMT in lung cancer." (PMID 35897813, 2022). "Additionally, TCF4 interacts with TWIST1, promotes EMT and TGFβ1 signalling, and subsequently enhances bone metastasis in KrasG12V-driven lung cancer." (PMID 35406121, 2022). "Nevertheless, the functional and mechanistic role of TCF4 as an oncogene or a tumor suppressor in lung cancer development and progression has not been investigated." (PMID 33917757, 2021). "In this study, we are to observe whether and how TCF-4 would regulate MMP-15 expression and their roles in the progression of lung cancer." (PMID 27046058, 2016). "Our results demonstrate the prognostic value of NIFK, and suggest that NIFK is required for lung cancer progression via the RUNX1-dependent CK1α repression, which activates TCF4/β-catenin signaling in metastasis and the Ki-67-dependent regulation in cell proliferation." (PMID 26984280, 2016). "As ID1 and TWIST1 share the binding domain of TCF4, PGC1α knock down-driven ID1 loss could not interfere with the TCF4-TWIST1 complex, and thus, induced EMT potential in the process of lung cancer metastasis." (PMID 33917757, 2021).